ALDH7A1P4 (aldehyde dehydrogenase 7 family member A1 pseudogene 4)
Synonyms: formerly ATQL4
Gene: Processed pseudogene on chromosome 10 (62,741,208 to 62,741,385, reverse strand). Ensembl gene ENSG00000234489.
Diseases named in the same sentence as ALDH7A1P4 in open-access papers:
ALDH7A1P4 is named in the same sentence as 3 diseases in open-access papers, as found by Europe PMC text mining. Sharing a sentence is not in itself a finding about the gene and the disease.
ALDH7A1P4 shares sentences with these, for which no sentence is quoted: autoimmune disease (1 paper); rheumatoid arthritis (1); systemic lupus erythematosus (1).